IL6 (interleukin 6)
Diseases named in the same sentence as IL6 in open-access papers (continued):
Sharing a sentence is not in itself a finding about the gene and the disease.
Sepsis (continued). "Ulinastatin has been evaluated as a promising drug in the treatment of sepsis, due to the inhibition of various serine proteases, inflammatory mediators produced by neutrophils, and the production of TNF-α, IL-1, and IL-6." (PMID 29467017, 2018). "The IL-6, WBC and C-reactive protein (CRP) levels of the sepsis group and SIRS group were significantly higher than those of the control group (P < 0.05)." (PMID 29760745, 2018). "The characteristic of the first phase of sepsis is the production of proinflammatory cytokines, including tumor necrosis factor-alpha (TNF-α), interleukin- (IL-) 1β, IL-6, and IL-8." (PMID 29636842, 2018). "Firstly, the current study found that sepsis rats exhibited increased expressions of D-lactic acid, DAO, bacterial translocation, MDA, TNF-α, IL-6, and IL-10, in addition to decreased SOD activity." (PMID 30340459, 2018). "For example, IL-6, TNF-α, and HMGB1 levels are significantly higher in sepsis patients than in patients with other diseases or healthy people." (PMID 29780830, 2018). "We then measured the levels of proinflammatory cytokines (IL-6 and TNF), histones, and C5a in plasma from TLR3−/−, TLR9−/−, and Wt after inducing polymicrobial sepsis by CLP." (PMID 30364002, 2018). "Excessive release of inflammatory factors, such as IL-1β, IL-6, and TNF-α, triggered pathophysiological abnormities of sepsis." (PMID 28994737, 2017). "FC-99 protected mice in the CLP-induced polymicrobial sepsis model and significantly decreased the serum levels of TNF-α and IL-6." (PMID 28976923, 2017). "Additionally, knockout of IL-6 or TNF-α could not affect the loss of body weight during sepsis in mice." (PMID 28661460, 2017). "In the cecal ligation and puncture (CLP) model of sepsis, PPAR-γ agonist ameliorates systemic inflammation by decreasing plasma levels of TNF-α and IL-6 via inhibition of nuclear factor kappa B (NF-κB)." (PMID 28845215, 2017). "By flow cytometric analysis, they showed that the intracellular levels of IL-6 and TNF-α in patients with sepsis were significantly lower than those of healthy control subjects." (PMID 28274246, 2017). "Clinical sepsis scores were monitored; serum cytokines (TNF-α, IL-6, IL-10) and chemokines (MIP-1α) were measured at the end." (PMID 28759625, 2017). "The study further supports the usefulness of IL-8, IL-6, IL-10, and PCT as biomarkers of sepsis in febrile neutropenic children." (PMID 28769538, 2017). "We detected higher serum levels of cytokines TNF-α (5.7 vs. 0.7 pg/ml, P < 0.001), IL-6 (24.8 vs. 3.8 pg/ml, P < 0.001), IL-10 (30.0 vs. 11.9 pg/ml, P = 0.040), and VEGF (177.9 vs. 48.1 pg/ml, P = 0.018) in sepsis sera." (PMID 28086962, 2017). "The activation of NF-κB (p65) was proved to play important roles in the development and progression of sepsis through enhancing the transcription of various pro-inflammatory cytokines including TNF-α, IL-1β, IL-6." (PMID 28430592, 2017). "Serum levels of sTREM-1, IL-6, PCT, and CRP were significantly higher in patients with septic shock than in those with severe sepsis." (PMID 28380034, 2017). "Activation of NLRs and RLRs promote the assembly of inflammasomes 14 which mediate the release of inflammatory cytokines including TNF‐α, IL‐1, IL‐6, IL‐18, and HMGB1, which itself also possesses an inflammatory cytokine function in sepsis." (PMID 28186706, 2017). "With respect to the IL-6 and TNF-α, hemodynamic, and biochemical responses CLP model is the most comparable to human sepsis." (PMID 28976923, 2017). "The sepsis patients exhibited significantly higher plasma concentrations of TNF-α, IL-6 and IL-1β compared with the healthy controls." (PMID 28472164, 2017). "While plasma IL-6, TNF-α, and IL-1β levels are also reported as predictors of death from sepsis, in our study the utility of IL-8 was much greater." (PMID 28167592, 2017).
Sepsis (continued). "This study documents the endogenous production of IL-6, TNF-α and IL-10 in rats with cecal ligation and puncture (CLP) induced sepsis on conscious animals with intermittent blood sampling in the individual rat during a 72-h period." (PMID 29204105, 2017). "The concentrations of IL-1β, IL-6, and TNF-α were significantly higher in the sepsis groups than those in the NC group." (PMID 28513569, 2017). "Spermine inhibits the production of IL-12, TNF-α, IL-1, IL-6, MIP-1a, and MIP-1b by in vitro-stimulated macrophages and protects against lethal sepsis by attenuating local and systemic inflammatory response." (PMID 29137411, 2017). "During the early hyperinflammatory phase of sepsis, plasma levels of proinflammatory cytokines TNF-α and IL-6, as well as the chemokine monocyte chemoattractant protein 1 (MCP-1/CCL2), are dramatically increased." (PMID 28628637, 2017). "In the present study, salidroside treatment reversed both sepsis-induced downregulation of SIRT1 expression and increased proinflammatory cytokines (TNF-α and IL-6) secretion." (PMID 28931916, 2017). "Here, we found increased serum IL-6, CXCL1, and HMGB1 levels in sepsis survivors 2 weeks post-CLP when compared to sham controls." (PMID 29326685, 2017). "IL-6 and TNF-α were significantly increased in the sepsis group compared with the sham group, and this increase was reduced in the sepsis group treated with MSCs." (PMID 29273091, 2017). "The therapeutic effects of rSj-Cys treatment were associated with the significant reduction of pro-inflammatory cytokines (TNF-α, IL-1β and IL-6) and boost of IL-10 and TGF-β1 cytokines in sera of mice with sepsis." (PMID 28482922, 2017). "The concentration of inflammatory cytokines (TNF-a, IL-6, MCP-1 and IL-10) were dramatically increased in plasma and peritoneum in mice under sepsis." (PMID 28273909, 2017). "In accordance with this observation, MFG-E8 suppressed inflammation in sepsis and ischemia/reperfusion conditions with LPS-TLR4 signaling by reducing the production of proinflammatory cytokines such as TNF-α, IL-1β, and IL-6." (PMID 27429513, 2016). "Another limitation is inability to use other inflammatory markers as IL-6 and TNF-alpha besides CRP in comparison to PSP for early sepsis diagnosis." (PMID 27689072, 2016). "LPS can promote overexpression of proinflammatory cytokines including IL-6, IL-1β, and TNF-α, which was involved in subsequent sepsis." (PMID 28042205, 2016). "The inflammatory cytokines IL-6, IL-1β, and TNF-α have been well documented to increase mortality in sepsis." (PMID 27009867, 2016). "In TNF-α induced mouse systematic sepsis model, RIP3-KO mice recovered from hypothermia and survived longer, which was partly by reducing DAMPs and IL-1β, IL-6." (PMID 27195494, 2016). "Here, we demonstrate that methane-rich saline (MS) treatment can protect mice from LPS-induced endotoxin shock, bacteria-induced sepsis and DSS-induced colitis by suppressing TNF-α and IL-6 production." (PMID 27405597, 2016). "Since the essence of sepsis is the inflammatory reactions, we detected the productions of inflammatory cytokines, such as TNF-α, IL-1β, and IL-6, in kidney tissue by ELISA." (PMID 26904148, 2016). "During the early stages of sepsis, the body is at a proinflammatory stage accompanied by the release of a large number of proinflammatory cytokines such as TNF-α, IL-1β, and IL-6." (PMID 27195281, 2016). "In this study, the impact of tissue damage due to surgical interventions on the sepsis biomarkers suPAR, CRP, PCT, and IL-6 in patients treated for culture-proven bloodstream infection was investigated." (PMID 30671318, 2016). "Similar to the serum results, the concentration of IL-6, TNF-α, IL-1β and IL-1α in the colonic wall rose significantly following CLP-induced sepsis." (PMID 27044016, 2016).
Sepsis (continued). "Proinflammatory cytokines such as TNF-α, IL-6, IL-1, and IFN-γ play an important role during the course of sepsis, interfering with the prognosis, progression, and intensity of tissue damage, and are associated with the aggravation and lethality of sepsis." (PMID 27630733, 2016). "Inflammatory cytokines (TNF-α, IL-6, and HMGB1) were increased, while anti-inflammatory cytokines (IL-10) were decreased in sepsis." (PMID 27413421, 2016). "Blood was collected 24 hours before and after surgical intervention for determination of the sepsis biomarkers suPAR, CRP, PCT, and IL-6." (PMID 30671318, 2016). "CC homozygous patients showed lower sepsis-related organ failure assessment (SOFA) score, serum IL-6 levels and mortality at 30 days compared to those with other genotypes (GC or GG)." (PMID 27834822, 2016). "The administration of IDC-derived exosome containing MFG-E8 significantly suppressed the expression of proinflammatory cytokines, including TNF-α, IL-6, and High Mobility Group Box 1 (HMGB1), in CLP sepsis animals." (PMID 27429513, 2016). "In sepsis, cytokines like TNF-α, interleukin-1 beta (IL-1β) and IL-6 which are released after infection, play an important role in the inflammatory process." (PMID 27150961, 2016). "The elevated blood levels of IL-6 and MCP-1 after sepsis appeared to be reduced more by combined treatment with d-chlorpheniramine and famotidine than with famotidine alone." (PMID 27822777, 2016). "In the early stages of sepsis, the production of NO was decreased and the release of TNF-α, IL-6, and IL-1β was inhibited by citrulline supplementation." (PMID 27195281, 2016). "Systemic LPS injection results in a strong and immediate increase of several pro-inflammatory cytokines such as IL-6, TNF and IL-1β compared to a prolonged cytokine increase after CLP which resembles the progression and characteristics of human sepsis." (PMID 27437704, 2016). "Here we show that methane-rich saline (MS) ip treatment (16 ml/kg) alleviated endotoxin shock, bacteria-induced sepsis and dextran-sulfate-sodium-induced colitis in mice via decreased production of TNF-α and IL-6." (PMID 27405597, 2016). "In a multicenter study, the sensitivity of Presepsin for the diagnosis of sepsis was even higher at 91.9 %, significantly higher than PCT (89.9 %), IL6 (88.9 %) and blood cultures (35.4 %)." (PMID 27389015, 2016). "IL-6 and CRP are the most common markers aimed at determining the inflammatory response to the HepB vaccine in infants in order to prevent sepsis or other severe adverse reactions after injection." (PMID 27022211, 2016). "Acutely, sepsis increased TNF‐α and IL‐6 mRNA in muscle, and the increase in TNF‐α was significantly greater in ZM mice." (PMID 27811170, 2016). "Clinical signs of sepsis included increased body temperature, neutrophilia, increased C-reactive protein (CRP) and interleukin-6 (IL-6), and decreased serum iron." (PMID 26879530, 2016). "Among the sepsis patients, plasma NT-proBNP levels positively correlated with CRP (r = 0.544), procalcitonin (r = 0.815), TNF-α (r = 0.712), and IL6 (r = 0.682; P < 0.001 for all)." (PMID 26812689, 2016). "al., the cytokine secretions of TNF-α, IFN-γ, IL-6 and IL-10 were globally decreased after LPS and α-CD3/28 stimulation in patients who died from sepsis." (PMID 27056672, 2016). "It is reported that CD1d blockade prior to sepsis had a positive impact on survival in experimental CLP, which correlated with a decrease in spleen NKT cells and in circulating IL-6 and IL-10." (PMID 26114123, 2015). "Critically ill patients with evidence of systemic inflammation due to sepsis showed reduced HRV which was related to disease severity and increased systemic interleukin 6 (IL-6) levels." (PMID 25893426, 2015). "In contrast to the patients with sepsis, patients with chronic rheumatism presented a significant lower elevation of inflammatory markers such as CRP, leukocyte count, IL-6 and IL-10 (P<0.05) reflecting the moderate inflammatory condition." (PMID 25893429, 2015).
Sepsis (continued). "In the clinical sepsis group three infants (30.0%) had an increased CRP and one infant (10.0%) an increased IL-6." (PMID 25894336, 2015). "While the combination of PCT and IL6 yields a better prognostic value for sepsis, with IL6 serving to monitor effectiveness for antibiotic treatment, lower levels are found in SIRS compared to sepsis patients." (PMID 26263001, 2015). "Sepsis is mediated by early (tumor necrosis factor-α (TNF-α), interleukin-6 (IL-6)) and late (high mobility group box-1 (HMGB1)) inflammatory cytokines in response to infection." (PMID 25930108, 2015). "Plasma levels of interleukin 6, CRP, and procalcitonin reached their peaks on Day 0 (onset of sepsis) or Day 1 and declined rapidly thereafter despite the persistent severity." (PMID 26161427, 2015). "There is also anincreasing body of evidence supporting a direct anti-inflammatory role of MFG-E8 ininflammatory diseases such as acute lung injury, sepsis, and colitis.MFG-E8 reduces the expression of pro-inflammatory cytokines, including IL-1, IL-6, andTNF-α." (PMID 26375445, 2015). "In summary, this study demonstrated that CLP-induced sepsis promoted the expression of TLR4 and Myd88 and the activation of ERK1/2 and NF-κB in lung tissue, and ultimately induced the generation of TNF-α and IL-6 in BALF and plasma." (PMID 25929655, 2015). "Theoretically, proinflammatory cytokines (IL-6 and TNF-α) and anti-inflammatory cytokines (IL-4 and IL-10) are increased during sepsis even if IL-4 is often found at low levels probably owing to its short half-life in plasma (5–19 minutes)." (PMID 26635427, 2015). "Acute expression of individual cytokines and chemokines (such as IL-6, IL-8, MCP-1, and G-CSF) has been reported to correlate with the presence and severity of organ dysfunction in patients with severe sepsis and septic shock." (PMID 25882865, 2015). "To evaluate the neuroinflammation in the sepsis survivors, we measured TNF-α, IL-1β, IL-6, and IL-10 expressions in the PFC and hippocampus." (PMID 26416717, 2015). "Among the three patient subgroups, the severe sepsis patients displayed the highest CX3CL1 expression level, whereas the sepsis subtype patients displayed the lowest expression of TNF-a, IL-6 and IL-1β." (PMID 25888255, 2015). "As expected, in the present study CLP sepsis induced a serious systemic inflammatory response with significant increase of both pro-inflammatory cytokines TNF-α and IL-6 in the serum 6 h and 24 h after CLP." (PMID 26634656, 2015). "A recent study on sepsis patients compared plasma levels of TNF-α, IL-6 and IL-10 to immune-staining of freely circulating monocytes and leukocytes." (PMID 25958003, 2015). "The most used biomarkers for sepsis are procalcitonin (PCT), C-reactive protein (CRP), and interleukin 6 (IL-6)." (PMID 26221578, 2015). "Xia and colleagues have shown that Ash1l, a H3K4 methyltransferase, suppressed interleukin-6 (IL-6), and tumor necrosis factor (TNF) production in toll-like receptor (TLR)-triggered macrophages, protecting mice from sepsis." (PMID 26834738, 2015). "In 15 patients fulfilling the criteria for severe sepsis, we measured plasma-NGAL, plasma Crea and eGFR, CRP, leukocyte count as well as IL-6, IL-8 and IL-10." (PMID 25893429, 2015). "In the context of sepsis, research efforts have been directed toward molecules with the potential to affect inflammatory cytokines such as IL-6 and TNF-α, in order to alleviate SIRS during sepsis." (PMID 26599367, 2015). "It has also been shown that blockade of IL-6 and HMGB1 increases the survival of septic animals with established sepsis." (PMID 25930108, 2015). "In conclusion, the IL-6–174G/C polymorphism may not be associated with the risk of sepsis." (PMID 25734339, 2015). "Blood IL-6 and MFHAS1 concentrations were found to be significantly higher in the sepsis group than in the control group (p < 0.05)." (PMID 26599367, 2015).
Sepsis (continued). "Numerous cytokines and inflammatory mediators, including IL-1, IL-6, IL-12 and TNF-α, are documented to be released in the early phase of sepsis, while HMGB1 is released at the late phase." (PMID 25930108, 2015). "Since the generationof IL-6 and TNF-α is highly relevant to LPS/TLR4/MyD88/MAPK/NF-κB signal pathway in sepsis, therefore, we verified the effect of dexmedetomidine on these signal molecules in CLP-induced septic rats." (PMID 25929655, 2015). "Similar results were reported by other authors, which compared the levels of cytokines in patients with sepsis of differing origins; TNF-α and IL-6 levels were considerably greater in GNB patients." (PMID 26079127, 2015). "In this study, we used a mice model of lipopolysaccharide (LPS)-activated sepsis, mimicking what occurs in clinical sepsis, to investigate the effects of Dex and α-Bgt on spleen TNF-α, IL-6, and IL-1β release in vivo." (PMID 26702389, 2015). "The data indicate that patients with a poor outcome have enhanced IDO activity in the early stage of sepsis, leading to increased levels of KYN and KYNA, and provoking the expression of TGF-β and IL-6 and the development of endotoxin tolerance." (PMID 26881062, 2015). "This was based on the attenuation of IL-6 and superoxide production as well as the reduction of iNOS and caspase-3 expression in various tissues by SEL in animals with sepsis." (PMID 25268350, 2014). "Previous reports revealed that enteral GLN supplementation for 3 weeks decreased lung IL-6 levels and regulated the immune response during CLP-induced sepsis." (PMID 25022445, 2014). "Secretion levels of the spleen pro-inflammatory cytokines IL-1, IL-6, and TNF-α tallied significantly lower in comparison to the sepsis group, whereas secretion levels of IL-10 anti-inflammatory cytokine increased." (PMID 25153878, 2014). "Our results showed that Sirt1 deletion led to increased LPS-induced IL-6 and TNF-α production, suggesting that Sirt1 acts to suppress inflammatory responses during sepsis." (PMID 24896770, 2014). "The findings reported in the present study indicate that EA induces an anti-inflammatory mechanism that reduces TNF, IL-6, nitrite, and HMGB1 production in one of the more widely used rat models for studying polymicrobial sepsis." (PMID 25057275, 2014). "APN deficiency elicits the production of inflammatory mediators, including TNF-α, IL-6 and monocyte chemoattractant protein (MCP)-1 and aggravates sepsis-induced hepatic injury." (PMID 27602369, 2014). "Sepsis increased plasma levels of tumour necrosis factor alpha (TNF-α), interleukin 6 (IL-6) and IL-10." (PMID 25413250, 2014). "In a clinical report of 97 consecutive patients, 56% developed sepsis with about 26 pg/mL of TNF-α 37% had 20 pg/mL of IL-1 and in 80%; 415 pg/mL of IL-6 was detected, including a LPS mean concentration of 2.6 endotoxin units (EU)/mL (1 EU/mL = 0.6 ng/mL)." (PMID 24605247, 2014). "Administration of rosiglitazone, which increased the plasma APN concentration, significantly lowered plasma levels of inflammatory mediators, including TNF-α, IL-6, and MCP-1 during sepsis." (PMID 27602369, 2014). "Clinical and experimental studies have shown that LPS-induced sepsis can lead to a rapid simultaneous secretion of two functionally heterogeneous groups of cytokines: pro-inflammatory cytokines (e.g., TNF-α, IL-1β and IL-6) and anti-inflammatory (e.g., IL-10)." (PMID 24904237, 2014). "When insulin was injected at 4.8 mU · kg-1 · min-1 for 6 h, the IL-6 and TNF-a levels decreased significantly in the cortex, hypothalamus, and hippocampus (vs. sepsis group, p < 0.05)." (PMID 25093012, 2014). "Effects were related to a blocked nitrate/nitrite level increase whereas IL-6, ICAM-1, and IL-10 were similarly induced in all sepsis groups." (PMID 26266921, 2014).